TNFSF10 (TNF superfamily member 10)
Diseases named in the same sentence as TNFSF10 in open-access papers (continued):
Sharing a sentence is not in itself a finding about the gene and the disease.
kidney diseases (6 papers, 2014 to 2025). "In contrast, the proapoptotic, anoikis-related gene TNFSF10, which encodes the TNF-related apoptosis-inducing ligand (TRAIL), was consistently upregulated across all disease groups, indicating a propensity for cell death, particularly in kidney diseases with strong inflammatory components." (PMID 40072109, 2025). "Up to date, it is still difficult to conclude about the actual role of TNFSF10 in the development and progression of kidney diseases." (PMID 34356656, 2021). "These contradictory statements might be related to different regulation of TNFSF10 among various kinds and stages of kidney diseases." (PMID 34356656, 2021). "Otherwise, the inconsistent effects of TNFSF10 on kidney diseases also have been reported." (PMID 34356656, 2021). "Therefore, we have obtained new perceptions by realizing the unique regulation of miR-545-3p–TNFSF10, from which we can interpret kidney disease progression." (PMID 34356656, 2021). "Experimental and clinical studies have illustrated that TNFSF10/TRAIL is up-regulated in different kidney diseases, both in DN and in non-diabetic conditions such as LN, rejected kidney transplant, AKI, and others." (PMID 35806457, 2022). "However, the role of TNFSF10 in kidney diseases has not been fully explored." (PMID 34356656, 2021).
TNFSF10 also shares sentences with these, for which no sentence is quoted: glioma (169 papers); glioblastoma (159); colorectal cancer (147); non-small cell lung carcinoma (75); renal carcinoma (65); multiple myeloma (63); cervical carcinoma (46); lymphoma (43); atherosclerosis (42); Autoimmunity (30); acute myeloid leukemia (27); lung adenocarcinoma (27); cardiovascular disease (25); liver fibrosis (24); brain tumor (22); coronary artery disease (22); influenza (22); Ewing sarcoma (19); renal cell carcinoma (18); malignant glioma (17); sarcoma (17); acute lymphoblastic leukemia (16); adenocarcinoma (16); Arthritis (15); chronic lymphocytic leukemia (14); chronic myeloid leukemia (14); HIV-1 infection (13); thyroid cancer (13); colorectal tumor (12); head and neck cancer (12).
A further 366 diseases each share a sentence with TNFSF10 in 11 papers or fewer.